CREB1 (cAMP responsive element binding protein 1)
Diseases named in the same sentence as CREB1 in open-access papers (continued):
Sharing a sentence is not in itself a finding about the gene and the disease.
breast cancer (continued). "MTT and Colony formation assays showed that knockdown of CREB1 significantly inhibited the proliferative capacity of breast cancer cells MCF-7 and MDA-MB-231." (PMID 31754343, 2019). "The results showed that the expression levels of CREB1 in tumor cell lines and breast cancer tissues were significantly higher than that of normal cell lines and breast tissues." (PMID 31754343, 2019). "To further demonstrate the results, we examined the expression of CREB1 mRNA in breast cancer tissues and cell lines by qPCR." (PMID 31754343, 2019). "To confirm and characterize further the positive contribution of CREB1 to ERα activity, we performed luciferase reporter assays with the human ERα-positive breast cancer cell line MDA-MB-134." (PMID 30456355, 2018). "We found nuclear accumulation of phosphorylated CREB1 in the tumor vascular endothelium of human breast cancer, indicating chronic activation of cAMP signaling in these vessels." (PMID 29775418, 2018). "Overall, these findings are consistent with the notion that a functional ERα/CREB1 interplay is a positive predictor in breast cancer." (PMID 30456355, 2018). "The level of Creb1 in breast cancer patients is elevated and is significantly up-regulated in patients with a poor prognosis, metastatic disease, and nodal involvement." (PMID 28467448, 2017). "Even in case of CREB1 gene, the duration required for alteration of gene expression seems to be more than 24 h as indicated by a study assessing the effects of CREB1 gene knockout in case of human breast cancer cells." (PMID 29209221, 2017). "Lastly, miR-27b-3p levels were found to be significantly negatively correlated with both NR5A2 and CREB1 levels in breast cancer tissues." (PMID 27809310, 2016). "Abnormal expression of CREB1 was observed in many cancers including acute myeloid leukemia, breast cancer, non-small cell lung carcinoma and renal cancer." (PMID 27801665, 2016). "Our results showed that miR-27b-3p mimics significantly attenuated both protein and mRNA levels of NR5A2 and CREB1, whereas miR-509-5p inhibitors observably enhanced the protein and mRNA levels of the two genes in all the four breast cancer cells." (PMID 27809310, 2016). "Consistently, CREB1 was previously found to be an unfavorable prognostic factor for patients with non-small cell lung cancer, breast cancer and hepatocellular carcinoma." (PMID 25825983, 2015). "Our study identified the core promoter region responsible for constitutive expression of LAPTM4B and clarified that CREB1 played an important role in LAPTM4B transcriptional regulation in human breast cancer cells." (PMID 23469012, 2013). "Importantly, CHDH expression in breast cancer is also regulated by oestrogen; both CHDH and acetylcholine are involved in choline metabolism, suggesting a potential association between CREB1 and CHDH." (PMID 40928004, 2025). "Moreover, Cox repression indicates that phospho-CREB1/ATF1 intensity is an independent factor in determining disease-free status in breast cancer (P < 0.001)." (PMID 37463926, 2023). "Moreover, CREB1 was found to reduce the apoptosis process and increase cell proliferation in breast cancer; whereas, PRKACA plays a key role in tumorigenesis and development of BC." (PMID 33910530, 2021). "In summary, we found that CREB1 regulated VASP expression in two ways in breast cancer." (PMID 31754343, 2019). "Our study explained the mechanism of CREB1/Lin28/miR-638/VASP network promoting the development of breast cancer, which further elucidated the mechanism of VASP as a key oncogene, and also provided a theoretical basis for expanding new approaches to tumor biotherapy." (PMID 31754343, 2019). "Moreover, miR-27b levels are also reduced in tamoxifen-resistant breast cancer cell lines as well as patient samples, which are associated with the increased expression of miR-27b targets NR5A2/LRH1 and CREB1." (PMID 30214383, 2018).
breast cancer (continued). "The upregulation of miR-27b sensitization to tamoxifen in ER+ breast cancer cells was further associated with the suppression of direct targets, NR5A2/LRH1 and CREB1, which are implicated in tamoxifen resistance via the induction of ERα and aromatase, respectively." (PMID 30214383, 2018). "More importantly, we validated that miR-27b-3p directly targeted and inhibited the expression of nuclear receptor subfamily 5 group A member 2 (NR5A2) and cAMP-response element binding protein 1 (CREB1) and therefore augmented tamoxifen-induced cytotoxicity in breast cancer." (PMID 27809310, 2016). "Moreover more recently it has been shown that PKA mediates resistance to cancer therapy in breast cancer cells and that high level of CREB1 expression correlates with metastasis and tumor stage in gastric cancer as well as malignant glioma growth." (PMID 26978032, 2016). "To further examine whether miR-27b-3p levels were correlated with NR5A2 and CREB1, we analyzed NR5A2 and CREB1 mRNA levels in 32 breast cancer tissues from tamoxifen-untreated patients and 20 breast cancer tissues from tamoxifen-resistant patients by RT-PCR." (PMID 27809310, 2016). "Our work strongly suggests that epigenetic inhibitors and CREB-1 modulators may be used in the future to regulate autophagy in breast cancer cells." (PMID 26474850, 2015). "Recent studies showed that CREB1 involved in the occurrence of breast cancer." (PMID 23469012, 2013). "In breast cancer cells, low-dose AGEs activate ERK1/2 and CREB1 to enhance cancer cell proliferation and migration, and similar RAGE-dependent pro-proliferative and migratory effects were observed in the highly invasive breast cancer MDA-MB-231 cell line." (PMID 40352588, 2025). "AGE/RAGE pathways induced pro-tumorigenic proteins, such as ERK1/2 and cREB1 (cAMP response element-binding protein 1), and cancer progression and metastasis by MCF-7 breast cancer cells." (PMID 34199060, 2021). "For example, by interacting with CREBBP to promote the transcription of H3K27Ac and CREB1, LINC01857 promote the progression of breast cancer." (PMID 34425868, 2021). "Similar results could be obtained with MCF7 cells; the effects of overexpression of CREB1 or CREB1 mutants and of the shRNA-mediated knockdown of CREB1 on ERα recruitment to three target genes point out a comparable requirement for ERα in this unrelated ERα-positive breast cancer cell line." (PMID 30456355, 2018). "Being required for ERα function, high levels of CREB1 may contribute to prevent a tumorigenic evolution, notably for cancers that have not yet been treated with tamoxifen, toward more aggressive and therapy-resistant versions of breast cancer that are estrogen and ERα independent." (PMID 30456355, 2018). "All these results suggested that miR-27b-3p attenuated breast cancer cell resistance to TAM by repressing NR5A2 and CREB1." (PMID 27809310, 2016). "Results showed NR5A2, CREB1 and GOLM1 expression levels were significantly higher in tamoxifen-resistant breast cancer cells." (PMID 27809310, 2016). "As expected, this list contains numerous markers of breast cancer cells whose expression specificity was previously reported by other (notably ERBB3, XBP1, KRT18, IL6ST, CREB1, TFF1, TFF3)." (PMID 19104654, 2008). "Notably, CRE activity (ssGSEA scores of CREB1/ATF1 target gene set) is positively correlated with neural signals in both TCGA (pan-cancer) and METABRIC (breast cancer) datasets (r = 0.4777 and 0.4180 for TCGA and METABRIC, respectively)." (PMID 37463926, 2023). "We identified an increased presence of phosphoproteins such as p-AKT1, p-STAT3, p-SMAD3, p-CREB1, p-p38, p-PTN11, and p-ERK1 in mammary tumors compared to the mammary gland, which should be further investigated as potential novel biomarkers in mammary carcinogenesis." (PMID 37568820, 2023).
breast cancer (continued). "In breast cancer studies, CREB1 was found to be highly expressed in metastatic breast cancer cells compared to non-metastatic cells and promoted breast cancer metastasis and subsequent bone destruction." (PMID 33921660, 2021). "Furthermore, CREB1 can also directly bind to the promoter of VASP, and activate VASP expression, forming a CREB/Lin28/miR-638/VASP interactive network, which plays an important role in promoting cell proliferation and migration in breast cancer." (PMID 31754343, 2019). "Furthermore, we demonstrated that the reduction of miR-27b-3p conferred resistance to tamoxifen in breast cancers by increasing the NR5A2 and CREB1 levels." (PMID 27809310, 2016). "Similarly, GSE treatment led to the downregulation of two transcription factors: cyclic AMP-responsive element-binding protein-1 (CREB-1) and glucocorticoid receptor (GR), which upregulate the aromatase gene expression through the promoters I.3/II and I.4 in breast cancer." (PMID 37047797, 2023). "Our study elucidated the mechanisms of the CREB1/Lin28/miR-638/VASP interactive network in the development of breast cancer, further explained the mechanism of VASP as a key oncogene, and provided new ideas for targeted therapy research against breast cancer cells growth and metastasis." (PMID 31754343, 2019). "Furthermore, CHIP-Seq in breast cancer cells indicated that CREB1 was the target gene of ZNF217 and two binding sites in the promoter region of CREB1 could be recognized by ZNF21719." (PMID 28607476, 2017). "Furthermore, we validated that miR-27b-3p directly targeted and inhibited the expression of nuclear receptor subfamily 5 group A member 2 (NR5A2) and cAMP-response element binding protein 1 (CREB1) and therefore augmented tamoxifen-induced cytotoxicity in breast cancer." (PMID 27809310, 2016). "Predicted regulatory element sequences for NANOG, CREB1, CPBP, BEN, PREB-1, SOX10, and POU2F1 (OCT1) POU6F1 and MEIS1 were highly enriched in the promoter regions of the tissue context dependent genes suggesting their possible roles in stem cells proliferation in HER2-regulated breast cancer tissue." (PMID 25428913, 2015). "Although negative correlation between miR-26a-5p-CREB1 pair and miR-26a-5p - STK4 pair was observed in some cancers, there was no significant negative correlation in aggressive breast cancer tissues (data not shown)." (PMID 34141617, 2021). "The sections of breast cancer tissues and noncancerous normal portion of the breast tissues from the same patients were stained for CD31 and phospho-CREB1 (serine 133)." (PMID 29775418, 2018).
melanoma (134 papers, 2009 to 2026). A malignant, usually aggressive tumor composed of atypical, neoplastic melanocytes. "We aimed to elucidate the underlying mechanism of the CREB1/miR-495-3p/KPNA2 axis in melanoma progression." (PMID 36522613, 2022). "Our findings show that KPNA2 is highly expressed in melanoma tissues and cell lines and that CREB1 overexpression promotes KPNA2 expression." (PMID 36522613, 2022). "Overall, CREB1 targeted the promoter of miR-495-3p, and CREB1 was up-regulated in melanoma tissues and cells." (PMID 36522613, 2022). "Our findings illustrate that CREB1 regulates KPNA2 by inhibiting miR-495-3p transcription to control melanoma progression." (PMID 36522613, 2022). "The ChIP assay also showed the physical interaction between CREB1 and the promoter of miR-495-3p in melanoma cells." (PMID 36522613, 2022). "In conclusion, CREB1 overexpression enhanced melanoma cell viability by inhibiting miR-495-3p transcription." (PMID 36522613, 2022). "CREB1 has been shown to be involved in the regulation of various malignant tumours, including melanoma." (PMID 36522613, 2022). "Multiple studies have affirmed the positive regulation of MITF transcription by CREB1 in malignant melanoma." (PMID 36268034, 2022). "This idea is further perpetuated by various studies showing that CREB1 directly upregulates MITF expression in human melanocytes or melanoma cultures." (PMID 36268034, 2022). "In summary, our research illustrates that CREB1 regulates KPNA2 by inhibiting miR-495-3p transcription to regulate melanoma progression." (PMID 36522613, 2022). "Our results indicate the molecular mechanism by which the CREB1/miR-495-3p/KPNA2 axis regulates melanoma progression." (PMID 36522613, 2022). "Our study demonstrates for the first time that CREB1 participates in the regulation of melanoma progression through the miR-495-3p/KPNA2 axis." (PMID 36522613, 2022). "Our study is the first to demonstrate that CREB1 is involved in the regulation of melanoma progression through transcriptional control of miR-495-3p." (PMID 36522613, 2022). "Our findings highlight the specific molecular mechanism by which the CREB1/miR-495-3p/KPNA2 axis regulates melanoma progression." (PMID 36522613, 2022). "CREB1 targeted miR-495-3p, and CREB1 overexpression enhanced melanoma cell viability by inhibiting miR-495-3p transcription." (PMID 36522613, 2022). "miR-203 promotes melanogenesis through the CREB1/MITF/Rab27a pathway by targeting Kif5b in melanoma." (PMID 34831071, 2021). "In hematopoietic (e.g. acute myeloid leukemia) and some solid tumors (e.g. melanoma, glioblastoma) CREB1 was found to be overexpressed resulting in increased cell proliferation, suppressed apoptosis, and enhanced angiogenesis and differentiation." (PMID 32300145, 2020). "CREB1 plays an important role in regulating MUC18 in the metastatic pathway of melanoma cells, and CREB1 overexpression correlates with acute myeloid leukemia (AML)." (PMID 26472185, 2015). "An inverse correlation between miR‐203a and CREB1 expression was observed in melanoma." (PMID 37565725, 2023). "Moreover, qRT‒PCR analysis showed that CREB1 was significantly up-regulated in melanoma tissues and cells, especially in A375 and B16 cells." (PMID 36522613, 2022). "Moreover, functional experiments further showed that CREB1 regulates KPNA2 by inhibiting miR-495-3p transcription to enhance melanoma cell viability." (PMID 36522613, 2022). "Moreover, miR-495-3p targeted KPNA2, and CREB1 regulated KPNA2 by inhibiting miR-495-3p transcription to enhance melanoma cell viability." (PMID 36522613, 2022). "Therefore, we conclude that CREB1 regulated KPNA2 by inhibiting miR-495-3p transcription to enhance melanoma cell viability." (PMID 36522613, 2022). "We mainly clarify the role of the CREB1/miR-495-3p/KPNA2 axis in melanoma." (PMID 36522613, 2022). "CREB1 regulates KPNA2 by inhibiting miR-495-3p transcription to control melanoma progression." (PMID 36522613, 2022).
melanoma (continued). "Moreover, CREB1 was down-regulated in melanoma tissues and cell lines, and CREB1 overexpression enhanced melanoma cell viability by inhibiting miR-495-3p transcription." (PMID 36522613, 2022). "We aimed to explore the potential molecular mechanisms by which CREB1 regulates melanoma." (PMID 36522613, 2022). "However, the specific mechanism of the CREB1/miR-495-3p axis in melanoma progression is unclear." (PMID 36522613, 2022). "This study on the function of the CREB1/miR-495-3p/KPNA2 axis in the development and metastasis of melanoma provides new insight into the pathogenesis of melanoma and a promising method for the treatment of melanoma." (PMID 36522613, 2022). "This study showed that PE may target CREB1 and thus regulate the MITF/TYR/DCT axis to reduce melanoma cell viability and the production of melanin." (PMID 40369904, 2025). "In summary, we hypothesized that the transcription factor CREB1 increases KPNA2 expression by inhibiting miR-495-3p transcription, which in turn promotes the development and metastasis of melanoma cells." (PMID 36522613, 2022). "Thus, we believe that our results will require confirmation in a further larger epidemiological study in our population and others, and quantitative and functional analyses of ADCY3, CREB1 and MITF SNVs in melanoma cells." (PMID 32699307, 2020).
Anxiety (121 papers, 2005 to 2026). Intense feelings of nervousness, tension, or panic often arise in response to interpersonal stresses. "Genetic variations in Creb1 have been strongly linked to anxiety disorders in humans, and Creb1 mutant mice have been reported to display increased anxiety-like behavior in various behavioral models." (PMID 38410679, 2024). "This alteration along the gut-brain axis influenced microRNAs, including mmu-miR-488-3p in the prefrontal cortex, ultimately impacting Creb1 and its associated signaling pathways, thereby regulating anxiety-like behavior." (PMID 38410679, 2024). "It is highly conceivable that the regulatory effect of mmu-miR-10a-5p, mmu-miR-488-3p, and mmu-miR-1224-5p on anxiety-like behavior induced by fecal transplantation is implemented through Creb1-mediated signaling pathways such as AMPK, cAMP, and PI3K-Akt." (PMID 38410679, 2024). "A total of 3 key target genes, regulated by the corresponding miRNAs, were involved in anxiety-related pathways, with Creb1 being the most critical as it was enriched in 4 anxiety-related pathways." (PMID 38410679, 2024). "Collectively, our study suggests that mmu-miR-10a-5p, mmu-miR-488-3p, and mmu-miR-1224-5p may modulate anxiety-like behavior through AMPK, cAMP, PI3K-Akt signaling pathways involving Creb1 following fecal transplantation from mice with anxiety disorders." (PMID 38410679, 2024). "This increase, in turn, may have led to a decrease in Creb1 expression, interfering with the development of AMPK, cAMP, PI3K-Akt signaling pathways, and the Dopaminergic synapse, ultimately regulating anxiety-like behavior." (PMID 38410679, 2024).
memory impairment (110 papers, 2013 to 2026). "Acknowledging the role of CREB in TLE associated cognitive decline, we hypothesize that CREB-1 plausibly contribute to the memory impairment in the second hit PTZ group as evidenced by an increased expression." (PMID 33732146, 2020). "As predicted by network pharmacology methods, CASP3, BDNF, MAPK3, CREB1, and DRD2 were the hub genes in krill oil to alleviate METH-induced memory impairment." (PMID 34776973, 2021). "The decreased expression of CREB-1 and upregulated expression of NPY by mAb 1, mAb 2.5, and mAb 5 group reflects the amelioration of second hit PTZ induced memory impairment." (PMID 33732146, 2020).
Alzheimer disease (90 papers, 2009 to 2026). A progressive, neurodegenerative disease characterized by loss of function and death of nerve cells in several areas of the brain leading to loss of cognitive function such as memory and language. "The result implicated CREB1 and CBP as the culprit in the pathophysiology of Alzheimer’s disease (AD), yet further research could be done on a much larger population to confirm these observations." (PMID 33394237, 2021). "In Alzheimer’s disease, CBP activator (CREB1), together with CBP, enhances memory formation and learning." (PMID 33394237, 2021).